RACK1 (receptor for activated C kinase 1)
Diseases named in the same sentence as RACK1 in open-access papers (continued):
Sharing a sentence is not in itself a finding about the gene and the disease.
colon cancer (continued). "Although RACK1 is considered to play a role in the development and progression of human cancer, the role and mechanisms of RACK1 in the pathogenesis of human colon cancer are poorly understood." (PMID 30451832, 2018). "Subcutaneous tumor formation experiment showed that RACK1 overexpression significantly increased while knockdown significantly decreased the growth of colon cancer cells in nude mice." (PMID 30451832, 2018). "Our data suggest that RACK1 acts as an oncogene in colon cancer, and RACK1-induced autophagy promotes proliferation and survival of colon cancer, highlighting the therapeutic potential of autophagy inhibitor in the colon cancer with high RACK1 expression." (PMID 30451832, 2018). "Flow cytometric analysis showed that both siRNAs blocked RACK1 OE colon cancer cell cycle at G1/S phase, and significantly increased RACK1 OE colon cancer cell apoptosis as compared to control siRNA." (PMID 30451832, 2018). "Flow cytometric analysis of cell apoptosis showed that RACK1 overexpression significantly decreased while knockdown significantly increased colon cancer cell apoptosis." (PMID 30451832, 2018). "The results demonstrate that RACK1 increases anchorage-independent growth and in vivo tumorigenicity of colon cancer cells." (PMID 30451832, 2018). "Together, our results indicate that high RACK1 expression promotes tumorigenicity of colon cancer cells possibly through increasing colon cancer cell proliferation and inhibiting colon cancer cell apoptosis." (PMID 30451832, 2018). "The results showed that 3-MA also decreased cells proliferation, blocked cell cycle at G1/S phase and increased cells apoptosis in the RACK1 OE colon cancer cells." (PMID 30451832, 2018). "CCK-8, plate colony formation, and EdU incorporation labeling assay showed that RACK1 overexpression significantly increased while knockdown significantly decreased colon cancer cell proliferation." (PMID 30451832, 2018). "The results strongly indicate that RACK1 overexpression enhances the autophagic flux of colon cancer cells." (PMID 30451832, 2018). "Soft agar colony formation assay and subcutaneous tumor formation experiment in nude mice were performed to determine the effects of RACK1 on the anchorage-independent growth and in vitro tumorigenicity of colon cancer cells respectively." (PMID 30451832, 2018). "In apoptosis-resistant SW620 cell, derived from a primary colon cancer, Rack1 overexpression led to downregulation of FEM1b, an intracellular pro-apoptotic protein, by promoting its ubiquitination." (PMID 27644318, 2016). "Similarly, the ubiquitin E3 ligase RAB40C regulates the degradation of RACK1 in colon cancer cell lines." (PMID 37848434, 2023). "In addition, there are also contradictory reports on the role of RACK1 in colon cancer, with pro- and anti-cancer effects, respectively." (PMID 37848434, 2023). "Survival analysis for colon cancer patients was performed based on the RACK1 levels." (PMID 30451832, 2018). "Our data demonstrate that RACK1 acts as an oncogene in colon cancer, and suggest that RACK1-induced autophagy might be involved in the pathogenesis of colon cancer." (PMID 30451832, 2018). "In the present study, it is of interest to disclose how RACK1 functions in colon cancer." (PMID 30451832, 2018). "Moreover, we found that RACK1-induced autophagy of colon cancer cells; RACK1-induced autophagy promoted colon cancer cell proliferation and inhibited colon cancer cell apoptosis." (PMID 30451832, 2018). "We found that high RACK1 expression promoted colon cancer cell autophagy." (PMID 30451832, 2018). "Besides, RACK1 OE colon cancer cells were transfected with a plasmid-expressing EGFP fused with LC3 (EGFP-LC3) for 24 h and BAF treatment for an additional 24 h, thereafter the number of EGFP-LC3 puncta was examined." (PMID 30451832, 2018). "The role and mechanisms of RACK1 in the pathogenesis of colon cancer need to be further elucidated." (PMID 30451832, 2018).
colon cancer (continued). "Our data demonstrate for the first time that RACK1-induced autophagy that might be involved in the pathogenesis of colon cancer." (PMID 30451832, 2018). "Therefore, we presume that RACK1 induces colon cancer cell autophagy by activating JNK signaling pathway." (PMID 30451832, 2018). "Moreover, we used 3-methyladenine (3-MA), a class III phosphatidylinositol 3-kinase (PtdIns3K) inhibitor, to inhibit autophagy in the RACK1 OE colon cancer cells, and analyzed the changes of cells proliferation and apoptosis." (PMID 30451832, 2018). "Moreover, we found that RACK1-induced colon cancer cell autophagy, and RACK1-induced autophagy promoted colon cancer cell proliferation and inhibited colon cancer cell apoptosis." (PMID 30451832, 2018). "Moreover, we observed that RACK1 overexpression significantly increased while knockdown significantly decreased the anchorage-independent and xenograft growth of colon cancer cells." (PMID 30451832, 2018). "Interestingly, RACK1 has the opposite effect in colon cancer cells; RACK1 overexpression delays passage of HT-29 cells through G1 and mitotic checkpoints by suppressing Src-mediated Sam68 phosphorylation and maintaining the active state of CDK1-cyclinB." (PMID 28465488, 2017). "The Receptor for Activated C Kinase 1 (Rack1), a member of the tryptophan-aspartate repeat (WD-repeat) family proteins, was found to bind the N-terminus of Fem1b and poly-ubiquitinated Fem1b for proteasomal degradation in colon cancer cells." (PMID 27222660, 2016). "Therefore, the purpose of this study is to demonstrate the role of RACK1 in colon cancer." (PMID 30962803, 2019). "Moreover, we observed that RACK1 overexpression enhanced the autophagic flux of colon cancer cells." (PMID 30451832, 2018). "Therefore, we investigated the regulation of RACK1 on autophagy of colon cancer cells." (PMID 30451832, 2018). "Therefore high RACK1 expression may be involved in the pathogenesis of colon cancer by inhibiting cells senescence." (PMID 30451832, 2018). "We show that silencing of RAB40C results in the upregulation of RACK1, which in turn can reduce proliferation and colony formation of HCT116 colon cancer cells and influence the migration of T cells." (PMID 30112187, 2018). "The results showed that RACK1 expression in the three (SW620, HCT116, and HRT18) of five colon cancer cell lines was obviously higher than that in normal colonic epithelia." (PMID 30451832, 2018). "In colon cancer cells, Rack1 inhibits apoptosis by directly interacting with FEM1 homolog b (FEM1b), an intracellular pro-apoptotic protein, and thus promoting its ubiquitination and degradation, while downregulation of Rack1 led to FEM1b-mediated apoptosis." (PMID 27644318, 2016). "To determine whether RACK1-induced autophagy promotes colon cancer cell proliferation and inhibits colon cancer cell apoptosis, we used siRNA against ATG5 or BECN1 to inhibit autophagy in the RACK1 OE colon cancer cells, and analyzed the changes of cells proliferation and apoptosis." (PMID 30451832, 2018).
prostate carcinoma (17 papers, 2010 to 2024). A carcinoma that arises from epithelial cells of the prostate gland. "Recent studies have revealed that the prognostic prostate cancer biomarker PSMA (through its interaction with scaffolding protein RACK1) can activate the PI3K-AKT pathway." (PMID 35086953, 2022). "Furthermore, a recent study found that suppressing TRPM7 prevented hypoxia-induced malignant migration and invasion of androgen-independent prostate cancer cells via increasing RACK1-mediated HIF-1alpha degradation." (PMID 35771152, 2022). "Additionally, TRPM8 reduces RACK1-mediated ubiquitination of HIF-1α to elevate HIF-1α expression during the hypoxic growth adaptation of prostate cancer cells." (PMID 33344232, 2020). "Studies have shown that in HEK293 cell and prostate cancer disease models, HSP90 and receptor for activated C kinase (RACK1) can competitively bind HIF1A, and then inhibit proteasomal pathway degradation." (PMID 38385089, 2024). "In a recent report, TRPM8-promoted hypoxic tumor growth in AR+ prostate carcinoma cells involves RACK1 binding to HIF-1α and RACK1-mediated ubiquitination of HIF-1α." (PMID 26512697, 2015). "In addition, binding of TPA to PKC activates PKC and its binding to RACK1, which in turn triggers translocation of RACK1 from the nucleus to the cytoplasm, inactivation of MCM7, and disintegration of the DNA replication initiation complex in prostate cancer." (PMID 28465488, 2017).
glioma (16 papers, 2010 to 2025). A benign or malignant brain and spinal cord tumor that arises from glial cells (astrocytes, oligodendrocytes, ependymal cells). "Recently, lncRNA EGFR-AS1 was found to be associated with migration, invasion and apoptosis of glioma cells by targeting miR-133b/RACK1." (PMID 36418931, 2022). "Moreover, we examined the effect and underlying molecular mechanisms of RACK1 in the regulation of the cell cycle, apoptosis, migration, and invasion in glioma U87 and U251 cells." (PMID 27763568, 2016). "However, the biological function and underlying mechanism of RACK1 in glioma remains poorly defined." (PMID 27763568, 2016). "Furthermore, overexpression of RACK1 was tightly associated with poor prognosis outcome of glioma patients and promoted cell proliferation, migration, and invasion, as well as inhibited apoptosis of glioma cells." (PMID 27763568, 2016). "The scaffolding protein GNB2L1/RACK1 is upregulated in gliomas and inhibits glioma cell differentiation." (PMID 38398114, 2024). "CNTN2, a cell adhesion protein, is a downstream protein of RACK1, which affects the growth and differentiation of glioma cells through the RTK/Ras/MAPK signaling pathway." (PMID 32328342, 2020). "With the increase of RACK1 expression, the malignancy of glioma showed an increasing tendency (*** p < 0.001, *** p < 0.001, *** p < 0.001 as compared with grade I glioma tissues)." (PMID 27763568, 2016). "To investigate the functional role of RACK1 in glioma, we measured its mRNA and protein expression levels in normal tissues and three glioblastoma cell lines (T98G, U87, and U251) with RT-PCR and Western blot." (PMID 27763568, 2016). "As apoptosis regulation was a potential contributing factor to tumor development and progression, we then examined the effects of RACK1 on the apoptosis of glioma cells by Annexin V FITC and PI double labeled (Annexin V-FITC/PI) staining assay." (PMID 27763568, 2016). "Collectively, these findings indicated that RACK1 played a significant functional role in the regulation of glioma cell migration and invasion." (PMID 27763568, 2016). "In the present study, we investigated the relationship of RACK1 with clinical characteristics as well as prognosis of glioma patients." (PMID 27763568, 2016). "In conclusion, our study demonstrated that RACK1 was dramatically elevated in glioma tissues and correlated with the histological malignancy of glioma." (PMID 27763568, 2016). "The up-regulation of RACK1 in glioma tissues was further confirmed by Western blot and immunohistochemical staining (IHC)." (PMID 27763568, 2016). "Here, we found that RACK1 was significantly up-regulated in glioma tissues compared with normal brain tissues, being closely related to clinical stage of glioma both in mRNA and protein levels." (PMID 27763568, 2016). "The data suggested that RACK1 was generally and dramatically up-regulated in glioma tissues, probably correlated with poor prognosis in glioma cases." (PMID 27763568, 2016). "To further explore the possible mechanism by which RACK1 promoted the glioma cell cycle, we then investigated the protein levels of G1/S transition key regulators, such as Cyclin D1 and CDK6." (PMID 27763568, 2016). "Wound healing and transwell assays were performed to investigate the functional role of RACK1 in migration and invasion of glioma cells." (PMID 27763568, 2016). "RACK1 translocated to the nucleus in glioma and neuroblastoma cell lines upon PKA activation by forskolin to mediate the expression of a brain-derived neurotrophic factor." (PMID 23305203, 2013). "In the central nervous system, some studies have shown that RACK1 promotes the proliferation and invasion of glioma cells and may also affect the differentiation and apoptosis of glioma cells, but so far there are no studies on RACK1 in meningiomas." (PMID 38398158, 2024).
glioma (continued). "In our study, we found that blocking the expression of RACK1 greatly inhibited migration and invasion ability of glioma cells, and discovered that knockdown of RACK1 significantly decreased the expression of EMT markers, such as MMP2 and MMP9, ZEB1, N-cadherin, and Integrin-β1." (PMID 27763568, 2016). "We observed positive immunoreactivity of RACK1 in different grades of human glioma tissues." (PMID 27763568, 2016). "In vitro functional assays indicated that silencing of RACK1 could dramatically promote apoptosis and inhibit cell proliferation, migration, and invasion of glioma cells." (PMID 27763568, 2016). "Subsequently, to investigate whether the repressive effect of RACK1-siRNAs in the proliferation of glioma cells was mediated by inhibiting cell cycle progression or promoting apoptosis, a flow cytometry analysis was performed." (PMID 27763568, 2016). "The expression of RACK1 was further detected by IHC in another 65 cases of glioma tissues." (PMID 27763568, 2016). "In addition, function and mechanism research was conducted in cell models to find out the crucial role of RACK1 in glioma." (PMID 27763568, 2016). "Moreover, with the increase of RACK1 mRNA expression, the malignancy of glioma showed an increasing tendency, and the expression level of RACK1 in grade IV was 4.27 times higher than grade I glioma tissues." (PMID 27763568, 2016). "In this study, we increased the sample size to 193 cases for RT-PCR, 90 cases for Western blot, and another 65 cases of glioma tissues were evaluated immunohistochemically to continually study the relationship between the overexpression of RACK1 and gliomas in depth." (PMID 27763568, 2016). "Collectively, our study revealed that RACK1 might act as a valuable prognostic biomarker and potential therapeutic target for glioma." (PMID 27763568, 2016). "Therefore, we conclude that high levels of RACK1 were correlated with the progression of glioma." (PMID 27763568, 2016). "However, the implication of RACK1 in glioma progression was still unclear." (PMID 27763568, 2016). "GNB2L1/RACK1 promotes cell migration and proliferation in neuroblastomas and gliomas." (PMID 38398114, 2024). "Furthermore, we investigated the relationship between RACK1 expression level and histological malignancy in 32 cases of grade I, 58 cases of grade II, 49 cases of grade III, and 34 cases of grade IV glioma tissues." (PMID 27763568, 2016). "Interestingly, glioma cancer cells have reduced levels of LTV1 and produce ribosomes lacking RPS3, RPS10, and RACK1." (PMID 33334055, 2020).
oral squamous cell carcinoma (16 papers, 2016 to 2026). "A study in patients with oral squamous cell carcinoma revealed that RACK1 promotes oral squamous cell carcinoma progression, and its expression is negatively correlated with prognosis in these patients." (PMID 40940922, 2025). "In oral squamous cell carcinoma, RACK1 decreased IL-6, CCL5, and CSF levels and increased the M2/M1 ratio in an NF-κB axis-dependent manner." (PMID 38315284, 2024). "In various cancer types, such as oral squamous cell carcinoma, gastric cancer and cervical cancer, RACK1 has emerged as a critical regulatory gene." (PMID 38451046, 2024). "In oral squamous cell carcinoma, RACK1 promotes M2‐like macrophage polarization, which together with the M2/M1 ratio, predicts poor tumour prognosis." (PMID 38451046, 2024). "In oral squamous cell carcinoma, a link has been shown with the protein receptor for activated C kinase 1 (RACK1)." (PMID 32670885, 2020). "Receptor for activated C kinase 1 (RACK1) has been shown to promote oral squamous cell carcinoma (OSCC) progression, and RACK1 expression levels have been negatively correlated with prognosis in patients with OSCC." (PMID 31997535, 2020). "GNB2L1 (RACK1 – target of miR-196b-5p) has been reported to promote progression of oral squamous cell carcinoma via the AKT/mTOR pathway and induces OSCC cell migration; invasion and metastasis." (PMID 29728663, 2018). "In oral squamous cell carcinoma (OSCC), PER1 inhibits glycolysis-mediated cell proliferation by forming a PER1/receptor for activated C kinase 1 (RACK1)/phosphatidylinositol 3-kinase (PI3K) complex, regulating PI3K stability, and modulating PI3K/protein kinase B (AKT) signaling-dependent mechanisms." (PMID 41451215, 2025).